INSIG2 (insulin induced gene 2)
Diseases named in the same sentence as INSIG2 in open-access papers (continued):
Sharing a sentence is not in itself a finding about the gene and the disease.
Obesity (continued). "First, genetic polymorphisms in the vitamin D receptor, insulin-induced gene 2 (INSIG2), and FTO genes (fat mass and obesity associated genes) have been linked to obesity and metabolic disorders." (PMID 18335103, 2008). "Case-control study of the INSIG2 rs7566605 and PFKP rs6602024 variants in relation to overweight and obesity." (PMID 18682847, 2008). "Animal data suggests a role for INSIG2 in increasing triglyceride level in rats, as well as linkage to obesity phenotypes in mice." (PMID 17465681, 2007). "Recently a large genetic association study showed evidence for association of the single nucleotide polymorphism (SNP) rs7566605, which lies 10 Kb 5' to the first exon of the insulin-induced gene 2 (INSIG-2), with obesity in several cohorts." (PMID 17137505, 2006). "The SREBF2 gene and INSIG2 may be candidate genes for risperidone-induced dyslipidemia, obesity, and cardiovascular diseases in psychotic disorder patients." (PMID 34683084, 2021). "In regard to the roles of SREBP2 and INSIG2 in lipid metabolism regulation, it is more likely that obesity and dyslipidemia susceptibility may be related to the polymorphisms of the SREBP2 gene and INSIG2." (PMID 34683084, 2021). "Further studies are required to determine the impact of the SREBF2 and INSIG2 allelic forms on the response of obesity and dyslipidemia in the cells of rats exposed to risperidone for the elucidation of the functional consequence of the SREBF2 gene and INSIG2 polymorphisms." (PMID 34683084, 2021). "Since obesity always co-occurs with dyslipidemia, the changes in the metabolism of adipocyte, owing to the polymorphisms in the SREBP2 gene and/or INSIG2, may lead to obesity and/or dyslipidemia." (PMID 34683084, 2021). "In contrast, our study observed a nonsignificant association with INSIG2 (rs17587100) and risperidone-induced obesity and/or dyslipidemia." (PMID 34683084, 2021). "In addition, 7 of the 17 (41.2%) GWAs-selected genes (FTO, TMEM18, INSIG2, FAIM2/BCDIN3, BDNF, SH2B1 and MC4R) were associated with obesity in this population." (PMID 23950976, 2013). "We then determined whether the frequencies of the more than 30 clinical parameters related to coronary artery disease and stent placement were different among patients with the three INSIG2 obesity/lipid SNP genotypes." (PMID 20920244, 2010). "There was no replicated association for the INSIG2 variant and either obesity or BMI observed for African-American participants in the ARIC, CARDIA, or GENOA studies." (PMID 19523229, 2009). "In summary, the results of an analysis of a sample of 24,722 individuals belonging to four cohorts do not support a major role for the INSIG2 rs7566605 variant as a determinant of obesity risk." (PMID 19523229, 2009). "This pooled analysis including all study designs does not provide evidence for overall association of the INSIG2 rs7566605 CC genotype with increased risk of obesity compared to the CG or GG genotypes." (PMID 19851442, 2009). "There was also no consistent evidence that the INSIG2 polymorphism is a determinant of obesity risk in studies including individuals of non-European descent." (PMID 19523229, 2009). "Therefore, this study attempts to assess the effect of rs7566605 near INSIG2 on both obesity- and cholesterol-related traits in Koreans." (PMID 19772594, 2009). "Still, if replicated common variation in INSIG2 might, contribute to common forms obesity through interaction with a low level of physical activity." (PMID 18682847, 2008). "Therefore, the aims of the present study are to validate the obesity-associations with the GWA identified INSIG2 rs7566605 and PFKP rs6602024 variants, through case-control studies and analyses of obesity-related quantitative traits." (PMID 18682847, 2008). "Several studies have failed to validate the initial GWA finding of the INSIG2 rs7566605 C-allele contributing to the pathogenesis of obesity." (PMID 18682847, 2008).
Obesity (continued). "Data mapping of quantitative trait loci in mice (QTL) for obesity related traits and their response to high fat diet data have shown linkage to the INSIG2 gene region and with obesity related traits such as fat depots (reproductive, renal, mesenteric, and inguinal) and serum cholesterol levels." (PMID 19105843, 2008). "The results of this analysis of the influence of rs7566605 in a racially and ethnically diverse sample of 24,722 participants drawn from two community based cohort studies, a family-based study, and a case-control study do not support a major role for the INSIG2 polymorphism in obesity risk." (PMID 19523229, 2009). "Therefore, we propose that INSIG2 (rs7566605) may not be a causal variant; other genetic polymorphisms might play an important role in the development of obesity and/or dyslipidemia." (PMID 34683084, 2021). "The significant genes in GWAS results (CALCR, PLAG1, INSIG2, PPARG, BMP5, S100A10) also have been identified to have relationship with growth performance and obesity of adipose tissue for pig and cattle." (PMID 33264312, 2020). "Due to the ability of the Insulin-induced gene 2 (INSIG2) to regulate adipogenesis and lipid storage, INSIG2 is a strong candidate gene for obesity." (PMID 25607990, 2015). "We found a 3-locus model involving 3 genes of INSIG-SCAP-SREBP pathway (INSIG2 rs9308762, SCAP rs12487736, and SREBP2 rs1883205) had significant gene-gene interaction on obesity (permutated P = 0.001)." (PMID 25028659, 2014). "In our study, the results of GMDR revealed that INSIG2 rs9308762, SCAP rs12487736, and SREBP2 rs1883205 of INSIG-SCAP-SREBP pathway have gene-gene interaction on obesity." (PMID 25028659, 2014). "Genetic variations in the obesity-related genes beta-2 adrenergic receptor (ADRB2), beta-3 adrenergic receptor (ADRB3), insulin induced gene 2 (INSIG2), and peroxisome proliferator-activated receptor gamma (PPARγ) are also included in our study." (PMID 22355322, 2012). "Also, unknown epistatic interaction of the rs7566605 with one or other (rare) polymorphisms could lead to association with the more extreme obesity phenotype, with the INSIG2 gene being part of a complex that functions as a biological entity (SREBP, SCAP, INSIG2)." (PMID 19851442, 2009). "However, when we conducted a GMDR analysis, we found the significant interaction of the three genes (INSIG2 rs9308762, SCAP rs12487736, and SREBP2 rs1883205) on obesity." (PMID 25028659, 2014). "The INSIG2 rs7566605 and PFKP rs6602024 polymorphisms play no apparent role in the development of common forms of obesity in the Danish population." (PMID 18682847, 2008). "Exploration of associations between genotypes and metabolic/obesity related variables in patients with PCOS revealed some evidence for an association of variants in FTO and TCF7L2, whereas no indication of association was observable for SNPs in INSIG2 and MC4R." (PMID 20092643, 2010). "We can thus conclude that common variation in INSIG2 and PFKP, both candidate genes arising from GWA studies, do not play a significant role in the pathogenesis of obesity in the Danish population." (PMID 18682847, 2008).
dyslipidemia (8 papers, 2014 to 2023). "This study provided evidence of an association between the genetic polymorphisms of SREBF2 (rs2267443) and INSIG2 (rs11123469) with dyslipidemia in Thai psychotic disorder patients receiving risperidone treatment." (PMID 34683084, 2021). "In regard to INSIG2 playing an essential role in the regulation of lipid metabolism, Liou and colleagues demonstrated that the C allele of the INSIG2 (rs11123469) polymorphism was significantly overrepresented in those with metabolic syndrome in patients treated with AAP drugs." (PMID 34683084, 2021). "In addition, INSIG2 presents three SNPs in the intronic region, i.e., rs7566605 (G/C), rs11123469 (T/C), and rs17587100 (A/C), which have been associated with an increased risk for weight gain and metabolic syndrome." (PMID 34683084, 2021). "In this study, three CpG sites in MBTPS1, two CpG sites in INSIG1, one CpG site in INSIG2, seven CpG sites in FBXW7, and six CpG sites in AMFR were found to be associated with dyslipidemia." (PMID 36570009, 2022). "Recently, interaction of INSIG1 and INSIG2 on antipsychotic induced metabolic syndrome was also reported." (PMID 25028659, 2014). "SREBF2 and INSIG2 might be candidate genes for dyslipidemia in people with autism spectrum disorder treated with risperidone." (PMID 38375208, 2023).
diabetes (7 papers, 2006 to 2024). "Indeed, INSIG2 gene has been implicated in diabetes pathogenesis." (PMID 36986146, 2023). "However, the relationship among rs7566605 SNP of INSIG-2, hypercholesterolemia, and mild cognitive impairment remains unclear in patients with type 2 diabetes mellitus." (PMID 32596317, 2020). "MiR-375 has been reported to inhibit diabetes by targeting the expression of mRNA targets of miR-375 such as Gephyrin (GPHN), Insulin induced gene 2 (INSIG2), Myotrophin (MTPN) and Eukaryotic translation elongation factor 1 (Eef1e1)." (PMID 30379973, 2018).
Hepatic steatosis (6 papers, 2016 to 2025). Steatosis is a term used to denote lipid accumulation within hepatocytes. "Amongst the top Toxicity functions was hepatic steatosis (p = 6.99x10-4) with associated genes including Acaca, Cbs, Ccnd1, Cyp4a11, Ddc, Gstp1, Insig2, Por and Rorc." (PMID 26968002, 2016). "Age induced hepatic steatosis is alleviated in INSIG2 elevated condition." (PMID 36944690, 2023). "Firstly, Insig2 KO and WT mice were fed with HFD diet for 8 weeks, all mice developed moderate hepatic steatosis." (PMID 40169542, 2025). "CD36 can also interact with insulin-induced gene-2 (INSIG2) to increase the level of SREBP1 synthesis, promote de novo synthesis of fatty acid and induce hepatic steatosis." (PMID 36594091, 2023). "Vagotomy + Cirrhosis groups showed higher hepatic steatosis due to higher SREBP1 and low Insig2 protein and altered activation of key genes involved in hepatic lipid metabolism and inflammation." (PMID 34248683, 2021). "Notably, we observed that neither Insig2 knockout nor overexpression altered the predominant determinant of hepatic steatosis during HFD feeding—TG." (PMID 40169542, 2025).
Insulin resistance (6 papers, 2010 to 2021). Increased resistance towards insulin, that is, diminished effectiveness of insulin in reducing blood glucose levels. "The overexpression of Dusp1, Insig2, and Lcn2 has been linked to the development of insulin resistance." (PMID 21187916, 2010). "The effects of diet composition on hepatic insulin resistance were evaluated by examining responses of insulin-regulated genes, many of which have roles in hepatic lipogenesis (Srebf1, Insig2, Acaca, Fasn, Scd1, and Gck)." (PMID 31061673, 2018). "Additionally, increased levels of NEFA in response to insulin resistance may activate transcription factors such as PPARα in the liver, which could also contribute to the regulation of genes such as G6pc, Angplt4, and Insig2." (PMID 30532187, 2018).
breast carcinoma (4 papers, 2010 to 2025). "Analysis of the survival curve revealed that the higher mevalonate pathway associated genes (HMGCR, HMGCS1 and INSIG2) levels were correlated with lower survival times for the breast cancer patients." (PMID 31138773, 2019). "There are some genetic association studies conducted on Bangladeshi Breast cancer and cervical cancer population to evaluate susceptible single nucleotide polymorphisms of INSIG2, HLA-DRB1, GCNT1P5, IL1β, IL4R, IL6, FGFR2, CYP1A1, ESR1 genes and disease outcome." (PMID 40920780, 2025). "Therefore, we speculate that INSIG2, a negative regulator of cholesterol uptake and biosynthesis might possibly when overexpressed in breast cancer by miR-223-5p increases effectiveness of endocrine therapy and eliminate drug resistance." (PMID 32577155, 2020).
hepatocellular carcinoma (4 papers, 2021 to 2025). A malignant tumor that arises from hepatocytes. "Knockout of INSIG1 or INSIG2 in human hepatoma Huh7 cells attenuated ATF4 protein upregulation, indicating that only one of the endogenous INSIGs, unlike overexpression of intrinsic INSIG1 or INSIG2, was insufficient for ATF4 induction." (PMID 34298014, 2021).
Hypercholesterolemia (4 papers, 2010 to 2020). An increased concentration of cholesterol in the blood. "The polymorphisms rs12464355 and rs7566605 of the INSIG2 gene have been implicated in hypercholesterolemia and aberrations of serum lipid parameters, especially LDL-C levels." (PMID 31795497, 2019). "One particularly interesting single nucleotide polymorphism (SNP) which is consistent with either G or C, located 10 kb upstream of INSIG-2 was reported to have the strongest association with hypercholesterolaemia." (PMID 23249523, 2012). "Moreover, the promoter of INSIG-2 rs7566605 SNP is associated with the prevalence of hypercholesterolemia." (PMID 32596317, 2020). "A stepwise logistic regression was then used to estimate the independent effects of different variables, as well as the INSIG2 genotype, on PVD in men ≥65 years and cerebrovascular disease in women ≥65 years, as well as history of hypercholesterolemia for both women and men < 65 years of age." (PMID 20920244, 2010).
pancreatic cancer (4 papers, 2014 to 2024). "An investigation has explicated the association of INSIG2 with pancreatic cancer." (PMID 33586351, 2021). "Previous studies demonstrated that INSIG2 serves as a positive prognostic biomarker for colon and pancreatic cancer." (PMID 39861074, 2024). "INSIG2 overexpression is related to the malignant phenotype of pancreatic cancer under hypoxic conditions." (PMID 33731794, 2021). "A novel 14-gene signature comprising CCDC148, SH3RF2, CACNA1D, POLD3, PARP1, AP1M2, C4orf19, ANO1, VGLL1, SCEL, INPP4B, NET1, INSIG2 and BVES and a corresponding risk score formula were established for pancreatic cancer risk stratification and prognosis prediction." (PMID 33731794, 2021).
asthma (3 papers, 2011 to 2016). "A three-way gene-gene interaction was elucidated between the gene coding glutathione S-transferase P (GSTP1), the gene coding interleukin-4 receptor alpha chain (IL4Ra) and the gene coding insulin induced gene 2 (INSIG2) on the risk of lifetime asthma." (PMID 22355322, 2012). "In contrast, SNP rs4448492 in the INSIG2 gene was associated (P = 0.002) with asthma in African American population." (PMID 21387019, 2011). "The results of this study suggest that GSTP1, INSIG2 and IL4Ra may influence the lifetime asthma susceptibility through gene-gene interactions in schoolchildren." (PMID 22355322, 2012). "We used the likelihood ratio tests to validate the gene-gene interactions between IL4Ra and INSIG2 on childhood asthma and the P-value was 0.029." (PMID 22355322, 2012). "In conclusion, our study suggests that gene-gene interactions may occur between different pathophysiological pathways and a significant three-way gene-gene interaction between GSTP1, INSIG2 and IL4Ra on childhood asthma." (PMID 22355322, 2012).
schizophrenia (3 papers, 2021 to 2024). A major psychotic disorder characterized by abnormalities in the perception or expression of reality. "SNP rs3828942 of LEP and rs17047718 of INSIG2 have been implicated in MetS in patients with schizophrenia." (PMID 38540239, 2024). "For instance, INSIG2 rs17047764 was shown to be associated with antipsychotic-related weight gain, whereas rs17587100, rs10490624, and rs17047764 localized within or near the INSIG2 gene had a strong association with clozapine-induced BMI gain in patients with schizophrenia." (PMID 35627229, 2022). "We would like to tentatively conclude that the INSIG2 gene is probably involved in the development of MetS in people with schizophrenia treated with antipsychotic drugs." (PMID 35627229, 2022). "The results of our study show that the LEP and INSIG2 genes can play an important role in the development of MetS in patients with schizophrenia." (PMID 35627229, 2022). "In our previous papers, it has been demonstrated that polymorphisms in insulin-induced gene 2 (INSIG2), LEP, FTO, dopamine D2 receptor (DRD2), and 5-HT receptor genes may contribute to the development of metabolic disorders in schizophrenia." (PMID 38540239, 2024).
steatosis (3 papers, 2020 to 2025). Increased lipid within the cytoplasm of cells. "Collectively, these findings indicated that Insig2 deficiency disrupted lipid metabolism and enhanced ferroptosis, exacerbating hepatic I/R injury in the context of steatosis." (PMID 40169542, 2025). "Employing mouse model with Insig2 knock-out or hepatocyte-specific overexpression and high-fat diets to induce steatosis, we subjected these mice to hepatic I/R injury." (PMID 40169542, 2025). "In the rat model of steatosis LT, we observed the transcriptional expression levels of Insig2 in the transplanted liver were significantly decreased during LT (GSE193764)." (PMID 40169542, 2025). "To investigate the specific mechanisms by which Insig2 regulates ferroptosis in steatosis hepatic I/R, we have identified a molecule—GPX4, which exhibited significant changes at both the transcriptional and protein levels from the sequencing data." (PMID 40169542, 2025). "As anticipated, the results demonstrated that I/R injury downregulated Insig2 expression in steatosis hepatocytes." (PMID 40169542, 2025). "We found that the elevated iron concentrations in serum and liver tissues, increased PTGS2 and ALOX12 expression, and higher hepatic MDA levels were observed in Insig2 KO mice following steatosis I/R injury compared to WT mice." (PMID 40169542, 2025). "In our study, the expression of Insig2 was found to be significantly downregulated in both rat liver transplantation and mouse model of I/R injury in steatotic liver, suggesting its potential role in regulating steatosis hepatic I/R injury." (PMID 40169542, 2025). "However, the function of Insig2 in steatosis graft injury remains to be elucidated." (PMID 40169542, 2025).
type 2 diabetes (3 papers, 2008 to 2024). "In analyses of gene-environment interactions comprising a total of 5,604 individuals from the population-based Inter99 cohort, excluding known type 2 diabetes patients, we found an interaction between INSIG2 rs7566605 genotype and the level of self-reported physical activity." (PMID 18682847, 2008).
cervical cancer (2 papers, 2021 to 2025). A primary or metastatic malignant neoplasm involving the cervix. "We have investigated and found the association of rs6726538 of INSIG2 with the risk of cervical cancer in the Bangladeshi population." (PMID 33586351, 2021). "Our study summarizes that INSIG2 rs6726538 (A; T), HLA‐DRB1 rs9272143 (T; C), and GCNT1P5 rs7780883 (G; A) polymorphisms are associated with cervical cancer development in the Bangladeshi population." (PMID 33586351, 2021). "GWAS with these three different novel variants (rs6726538 of INSIG2, rs9272143 of HLA‐DRB1, and rs7780883 of GCNT1P5) imposed the probability of cervical cancer progression." (PMID 33586351, 2021). "Our study found the association of INSIG2 rs6726538 (A; T), HLA‐DRB1 rs9272143 (T; C), and GCNT1P5 rs7780883 (G; A) polymorphisms with cervical cancer risk in the Bangladeshi population." (PMID 33586351, 2021). "We have carried out this case‐control study to investigate the association of INSIG2 rs6726538 (A; T), HLA‐DRB1 rs9272143 (T; C), and GCNT1P5 rs7780883 (G; A) with cervical cancer." (PMID 33586351, 2021). "Our study concludes that INSIG2 rs6726538, HLA‐DRB1 rs9272143, and GCNT1P5 rs7780883 polymorphisms may contribute to the development of cervical cancer in the Bangladeshi population." (PMID 33586351, 2021). "Howsoever, no previous studies are suggesting the involvement of INSIG2 in cervical cancer except a GWAS study." (PMID 33586351, 2021).